INS (insulin)
Diseases named in the same sentence as INS in open-access papers (continued):
Sharing a sentence is not in itself a finding about the gene and the disease.
diabetes (continued). "Patch-like insulin delivery devices such as V-Go are an important advancement in diabetes technology that can improve care for patients and support pharmacists and other healthcare professionals in achieving clinical performance indicators." (PMID 33202616, 2020). "Diabetes mellitus is a metabolic disorder resulting from an imperfection in insulin secretion and/or insulin activity." (PMID 32992919, 2020). "T2D patients with a more severe diabetes are more likely to be treated with insulin, and more severe diabetes can lead to decompensation." (PMID 32488499, 2020). "PRS for T1D can diagnose young adults with diabetes that will require insulin treatment in European cohorts, and this will be important to classify accurately patients, when clinical factor make incorrect diagnosis." (PMID 32131491, 2020). "This adipokine increases insulin sensitivity and improves glucose metabolism, particularly in the early stage of diabetes." (PMID 32899610, 2020). "Subgroup analysis showed that these associations were most pronounced for people who were diagnosed with diabetes at a younger age and for those who reported living with diabetes for a longer duration and used both oral glucose-lowering medication and insulin." (PMID 32671413, 2020). "Diabetes is a long-lasting endocrine disorder described as persistent hyperglycemia, which is often triggered by the entire or relative shortage of insulin production or insulin resistance." (PMID 32626781, 2020). "Diabetes mellitus is a cluster of progressive metabolic diseases that typically develop in midlife from inadequate insulin secretion or insulin action, which leads to hyperglycaemia and possibly long-term damage to multiple organs, including the blood vessels." (PMID 34321718, 2020). "Several investigations showed that STZ enters the pancreatic β-cells by glucose protein-2 transporter and disrupts the balance between antioxidant and oxidant systems damaging the insulin-producing islet β-cells and inducing the progression of diabetes." (PMID 31998774, 2020). "In this connection, they suggested that insulin signaling can be improved with the use of BACE1 inhibitors during diabetes." (PMID 32993632, 2020). "In our study, almost 13% of the patients utilizing only other medications than insulin or metformin in 2016 started using metformin or insulin in addition to other diabetes medications in 2017." (PMID 33246453, 2020). "Additional research into these receptors has provided crucial information on their links to acetate signaling and control of various aspects of metabolism, including links to diabetes and insulin release." (PMID 33304273, 2020). "Kruskal–Wallis testscomparing scores between the three groups were significant for the followingdrug classes: drugs for diabetes in general, oral hypoglycaemic drugs, insulin,anticoagulants and antithrombotic drugs, phytotherapy drugs and homoeopathicdrugs." (PMID 35173953, 2020). "As diabetes progresses and the target glycemic control is even challenging to achieve, insulin injection would be administered." (PMID 33076406, 2020). "We chose male Akita mice in the current study, since the Japanese population with diabetes is characterized by impaired insulin and relatively low BMI, compared to Western populations." (PMID 33362717, 2020). "The equality of the covariance matrix of dependent variables was satisfied, and the effects of independent variables (group, insulin treatment, glycemic control, gender) on HbA1c, TGFβ1 and the duration of diabetes were analyzed." (PMID 33334029, 2020). "Despite lower absolute insulin secretion in CC islets, comparable efficiency of reversing diabetes was observed after implantation in NOD-scid mice at comparable doses." (PMID 31839542, 2020). "Diminished immunity is highly related to diabetes mellitus, as was mentioned before due to decreased blood supply and increase insulin resistance." (PMID 32517367, 2020).
diabetes (continued). "American Diabetes Association (ADA) and European Association for the Study of Diabetes (EASD) positioned DPP-4i alongside with sulfonylureas, thiazolidinediones, GLP-1 agonists and insulin, as a second-line add-on to metformin in their general recommendation." (PMID 32566235, 2020). "DM can be divided into type 1 diabetes mellitus (T1DM), which is characterized by absolute insulin secretion dysfunction, and type 2 diabetes mellitus (T2DM), which is characterized by insulin resistance (IR) and relatively insufficient insulin secretion." (PMID 33061888, 2020). "Results showed that 51.2% of girls and 52.5% of boys had a familial history of diabetes and 23.3% of girls and 19% of boys reported medication usage (Non-insulin drugs)." (PMID 32252831, 2020). "Only one session of exercise is effective to transiently reduce capillary glycemia, insulin sensitivity, and ambulatory blood pressure in individuals with diabetes." (PMID 33250859, 2020). "By inhibiting sodium and glucose reabsorption from the proximal tubules, the improvement in insulin resistance and natriuresis improved the cardiovascular mortality in diabetes mellitus (DM) patients." (PMID 33105763, 2020). "Type 2 diabetes mellitus (T2DM) results from the body’s ineffective use of insulin, and most people with diabetes around the world have T2DM." (PMID 33447179, 2020). "The original HFSII-BS contained items about correct diabetes management behavior like item“Reduced my insulin when my blood sugar was low” and item of inappropriate behavior to avoid hypoglycemia like item“Limited my exercise/physical activity”." (PMID 32210481, 2020). "Among 53 patients over 45 years old with type 2 diabetes mellitus, 35 needed insulin treatment (66%), while 18 patients were on oral antidiabetic therapy (34%)." (PMID 33298009, 2020). "Diabetes was often treated with metformin, insulin and sulfonylurea (respectively 79%, 57% and 46%)." (PMID 32948184, 2020). "On the one hand, insulin loses the function to enhance cellular glucose uptake and utilization in diabetics, which is defined clinically as insulin resistance which promotes obesity." (PMID 32982969, 2020). "Lastly, adjusting for disease severity did not change the associations between poverty, Euclidean distance, sex, or age on visit adherence measures, however patients with diabetes on insulin had a higher OR of good visit adherence (STable 8, STable 9)." (PMID 33054756, 2020). "Studies have established cross-talk between integrin signaling and insulin activity, but more details of how integrin-dependent signaling impacts the pathophysiology of diabetes are needed." (PMID 32934005, 2020). "Of the 73 (25.3%) patients with diabetes on a sulfonylurea, 58 (20.07%) were on other oral agents (most commonly metformin) and/or insulin." (PMID 32385343, 2020). "In the present studies, we determined the effects of long‐term diabetes on the metabolome of bladder detrusor tissue in a rat model of T1D and the ability of insulin treatment to normalize these metabolic changes." (PMID 33200530, 2020). "In two of the included trials, women with diabetes were excluded, one trial excluded women treated with insulin, but included participants who had GDM controlled by diet (10%), whilst the participant inclusion criteria for the fourth trial was unclear." (PMID 31995603, 2020). "Diabetes is induced by the disorder of pancreatic insulin secretion or by the resistance of peripheral cells to the insulin action." (PMID 32824505, 2020). "Efforts should be made by all stakeholders to make basal bolus insulin regimen more affordable to all children with type 1 diabetes mellitus." (PMID 32874425, 2020). "Fascinatingly, SIRT1 together with AMPK are largely involved in the regulation of many cellular processes, including energy metabolism, cell cycle, insulin secretion, and apoptosis during the pathogenesis of diabetes." (PMID 32168855, 2020).
diabetes (continued). "Our scan of the diabetes literature for related insights indicated that even though diabetic patients have been injecting insulin in home settings for a long time, at-home disposal practices among this population are understudied." (PMID 32746860, 2020). "Type 2 diabetes mellitus is a chronic disease that is characterized by hyperglycemia, insulin resistance, and dysfunctional insulin secretion." (PMID 32824773, 2020). "Five patients (29%) discontinued GLP1RA—4 due to side effects and 1 was switched by primary care provider to insulin due to uncontrolled diabetes." (PMID 32095510, 2020). "We conclude that DBMSCs are potential candidate for the treatment of diabetes through a mechanism involving the reduction of inflammation and the secretion of insulin to lower glucose levels." (PMID 32077075, 2020). "Diabetes mellitus (DM) is a metabolic condition that is determined by continuous blood glucose increases due to impaired production and/or insulin action." (PMID 33375437, 2020). "Our data suggest that 2H6 T cells regulate their interactions with the insulin-specific B cells and alter the pathogenic VH125 B cells to favor TGFβ production by 2H6 T cells, and thus, mediate diabetes protection." (PMID 33262765, 2020). "Type 2 diabetes mellitus arises due to defective insulin activity in body tissues, defective insulin secretion from pancreas or a combination of the two." (PMID 32660625, 2020). "The pathophysiology of type 2 diabetes mellitus (T2DM) is characterized by not only insulin resistance and beta cell dysfunction, but also the abnormal regulation of glucagon secretion." (PMID 32215330, 2020). "Muscle, liver and glycogen metabolism can be normal in athletes with diabetes with good overall glucose management, and exercise performance can be facilitated by modifications to insulin dose and nutrition." (PMID 32533229, 2020). "When rats were fed for 20 days with HFD, part of the animals became obese and developed diabetes with increased blood d-glucose and blood insulin concentrations (DIO rats)." (PMID 32789766, 2020). "The DSQL captures the impact of detailed aspects of modern diabetes management (e.g., carbohydrate counting and flexible insulin dose adjustment) that is extensively used in evaluating quality of life in DM." (PMID 33106185, 2020). "Current therapeutic measures to treat diabetes include the use of insulin and other agents, such as amylin analogues, alpha glycosidase inhibitors, sulfonylureas, and biguanides." (PMID 33187275, 2020). "It was reported that either orexigenic neuropeptide galanin or anorexigenic hormone leptin caught benefit insulin sensitivity through increasing the translocation of glucose transporter 4 (GLUT4) in patients with diabetes." (PMID 32395890, 2020). "Diabetes mellitus is a chronic, metabolic disease which results from insulin resistance or defective insulin secretion." (PMID 31995586, 2020). "Adiponectin has anti-atherogenic and anti-inflammatory and insulin sensitizing properties and its plasma concentrations are decreased in obese individuals and type 2 diabetic mellitus (DM2)." (PMID 32197395, 2020). "An artificial pancreas (AP) is a device that automatically and continuously regulates insulin delivery to control the blood glucose level (BGL) in people with diabetes, primarily patients with diabetes mellitus type 1 (DM1)." (PMID 32792580, 2020). "Humalog U-200 insulin users were comprised mainly of older patients with diabetes complications and high HbA1c levels at the time of U-200 initiation." (PMID 32002193, 2020). "During obesity and diabetes, adipose tissue and pancreatic islets become infiltrated by macrophages and undergo inflammation that further impairs insulin signaling." (PMID 32117058, 2020). "In this regard, methionine restriction can improve insulin resistance and glucose homeostasis in diabetes." (PMID 32911736, 2020).
diabetes (continued). "Overall, the findings support the contention that patients with diabetes who develop HTG-induced acute pancreatitis are typically in poor glycemic control despite being on insulin treatment." (PMID 33193106, 2020). "The pre-diabetes stage is considered to reflect progressive peripheral resistance to insulin, being counterbalanced by increased insulin secretion by beta cells." (PMID 32128655, 2020). "Self-management is a crucial part of diabetes management, especially for those with insulin treatment." (PMID 32891126, 2020). "Diabetes mellitus is a group of disorders of carbohydrate metabolism, whose main feature is chronic hyperglycemia that results from defects of insulin secretion, insulin action, or a combination of those." (PMID 32155866, 2020). "Assuming the scenario to be true, the immune system action of removing the insulin producing β-cells would be an appropriate response to an infected cell, which thereby induces diabetes instead of being part of an autoimmune process." (PMID 32927606, 2020). "Insulin accounted for 18% of all out-of-pocket spending and less out-of-pocket spending than diabetes-related supplies." (PMID 32478819, 2020). "In in vivo models of insulin resistance and diabetes, PPARα activation reverses the pregnancy-related augmentation of glucose-stimulated insulin hypersecretion by increasing insulin sensitivity." (PMID 32708786, 2020). "It is characterized by hyperglycemia and defective production and/or secretion of insulin and complications in the heart, kidney, and neural system leading to death, which have drawn notable attention to the management of diabetes." (PMID 33041786, 2020). "Insulin sensitizers and insulin injection are helpful in relieving hyperglycemia but are less effective in relieving symptoms of diabetes complications." (PMID 32680569, 2020). "People with diabetes self-record detailed information including blood glucose levels, diet and insulin intake, physical activity, medication, and other parameters." (PMID 32784178, 2020). "Now, some oral agents such as sulfonylureas, metformin, sitagliptin phosphate (SP), and injection of insulin are extensively used in the treatment of type 2 diabetes mellitus (T2DM)." (PMID 32351607, 2020). "Afrezza® is marketed as an ultra-rapid-acting inhaled insulin indicated to improve the glycaemic control for adult patients with type 1 or 2 diabetes." (PMID 33114726, 2020). "Our study prompts rethinking of the benefits of acute insulin administration outside routinely scheduled treatments to include cases of acute pulmonary congestion in patients with diabetes." (PMID 32308680, 2020). "Diabetes mellitus is a chronic metabolic syndrome featured by elevated blood glucose levels results from inadequate production of the hormone insulin." (PMID 32345350, 2020). "In order to take proper countermeasures, such as exogenous insulin injections to contrast hyperglycemia, or fast-acting carbohydrates ingestion to balance hypoglycemia, individuals with diabetes need to frequently monitor BG by a portable device." (PMID 33097760, 2020). "Insulin resistance which occurs in type 2 diabetes mellitus is a situation that higher circulating insulin levels are necessary to achieve the integrated glucose-lowering response." (PMID 32509880, 2020). "Diabetes mellitus (DM) is a chronic endocrine-metabolic disease that is characterised by poor insulin secretion or by the inability of the body’s cells to respond to it." (PMID 32143452, 2020). "There is a clear need for an alternative to insulin and insulin analogs in the treatment of diabetes." (PMID 31378829, 2020). "Endothelial dysfunction is not only a consequence of insulin resistance, but also impairs insulin signaling to further reduce insulin sensitivity, thereby resulting in a destructive cycle in metabolic syndrome and diabetes." (PMID 32194403, 2020).
diabetes (continued). "Diabetes mellitus takes two main forms: T1D results from inadequate insulin secretion, and T2D results from poor insulin action on target cells, that is, insulin resistance." (PMID 33536868, 2020). "Diabetes mellitus represents a heterogeneous group of chronic metabolic disorders characterized by hyperglycaemia resulting from impaired insulin secretion or action." (PMID 32019118, 2020). "Taken together, glycaemia, insulin and leptin are key mechanistic components of the diabetes–atherosclerosis axis." (PMID 32816039, 2020). "Diabetes mellitus (DM) is a metabolic disease characterized by high blood glucose levels resulting from defects in insulin secretion, insulin action, or both." (PMID 33198690, 2020). "The first attempt to treat diabetes with oral insulin can date back to 1922 but the failure made researchers realize that the main obstacle to oral delivery of biomacromolecules was mainly from the human body itself." (PMID 32887466, 2020). "Phospho1 deficiency results in decreased blood glucose levels, improved insulin sensitivity, glucose tolerance and conferred protection from diet-induced obesity and diabetes in mice despite a 60-fold upregulation of Esp expression by Phospho1−/− osteoblasts." (PMID 33092598, 2020). "For this reason, enhancing or inducing the intrinsic regenerative ability of endocrine islets and developing new strategies to produce insulin-secreting β-cells will have profound consequences for the development of therapeutic treatments for diabetes." (PMID 33217903, 2020). "A different category of diabetes called gestational diabetes mellitus (GDM) is also insulin resistant but it occurs during pregnancy." (PMID 33255455, 2020). "Transplantation of insulin-producing cells derived from human embryonic stem cells (hESCs) has been proposed as a promising therapy for diabetes." (PMID 32345350, 2020). "The major case of HAT and HDAC effect on the diabetes was laid on the molecular mechanism of insulin transcription mediated by Pdx1." (PMID 32815547, 2020). "This is particularly true for those with diabetes, it is demanding on both patients and their families to adhere to multiple daily injections of insulin, glucose monitoring, and lifestyle modification." (PMID 32280715, 2020). "Conversely, reduction of body iron can restore insulin sensitivity, and epidemiological evidence suggests that it delays the onset of complications such as type 2 diabetes mellitus, cardiovascular disease, and advanced liver disease." (PMID 32625166, 2020). "Chronic inflammation and apoptosis of β cells will have a significant impact on the insulin signal of cells and eventually lead to diabetes." (PMID 32595730, 2020). "The diabetes subgroups shown in the present study, were based upon the calculation of the muscle insulin sensitivity index." (PMID 33003389, 2020). "Patients with diabetes at public facilities complained of low quality insulin brands being supplied." (PMID 32634164, 2020). "After STZ administration, successful induction of diabetes was confirmed by the persistence of fasting hyperglycemia and by the low level of C‐peptide and insulin." (PMID 32318663, 2020). "Data on diabetes management (insulin dose) and glycaemic control (HbA1c level) were available for six and five patients from diabetes onset, and for all patients from the most recent treatment year (follow-up)." (PMID 32321554, 2020). "Diabetes mellitus is an endocrine disease characterized by hyperglycemia which occurs as a result of the inability of the pancreas to secrete insulin, defects in insulin action, or both." (PMID 32410865, 2020). "It is also involved in glucose metabolism and homeostasis, insulin sensitivity, in the development of diabetes, and in adipogenesis." (PMID 32858998, 2020). "Both type 2 prediabetes/diabetes (T2DM) and new-onset prediabetes/diabetes after acute pancreatitis (NODAP) are characterized by impaired tissue sensitivity to insulin action." (PMID 32967240, 2020).